IL6 (interleukin 6)
Diseases named in the same sentence as IL6 in open-access papers (continued):
Sharing a sentence is not in itself a finding about the gene and the disease.
infection (continued). "Consistent with the expression of TLRs in the resistant and susceptible groups, the induction of IL-6 and IFN-β transcription was greatly enhanced in the resistant, but not in the susceptible chickens at 16 h post-infection." (PMID 22438967, 2012). "Further, exogenous treatment of IL-6, IL-13, and IFN-γ at day 3 postintracranial infection could induce mild PE and exacerbate pulmonary abnormality of EV71-infected mice." (PMID 22956971, 2012). "Taken together, these data indicate that the highly susceptible strains do not effectively clear S. aureus from the site of infection, do not mount an effective IL-6–mediated inflammatory response, and are subject to extensive bacterial dissemination." (PMID 22690378, 2012). "Therefore, we determined the expression of cytokines involved in neutrophil recruitment, including IL-6, G-CSF, and CXCL1, within the lungs of neutrophil depleted and isotype control antibody treated mice on day 7 post-infection with C. neoformans strain H99γ." (PMID 23216912, 2012). "Moreover, between 3–5 days after infection, the levels of IL-12p70, TNF-α and IL-6 were higher in mice immunized with one of the antigens than in mice immunized with both DnaK and Tul4, a pattern similar to that seen with the other cytokines assessed." (PMID 23209745, 2012). "Similarly, in vivo infection with IAV resulted in higher levels of primarily neutrophil attracting chemokines such as KC and MIP-2 and several proinflammatory cytokines such as IL-6, TNF and IL-1β in the lungs of A20myel-KO mice compared to wild type mice." (PMID 22396652, 2012). "IL-6, G-CSF, and CXCL1 were significantly increased in the lung homogenates of neutrophil depleted mice compared to lung homogenates of isotype control antibody treated mice, suggesting an attempt by the host to recruit neutrophils to the site of infection." (PMID 23216912, 2012). "IL1β, IL6, IL12 and TNFα act proinflammatory and are known to be secreted by activated microglia in many different conditions, such as neurodegenerative disease, trauma or infection." (PMID 22647544, 2012). "However, in contrast to untreated animals, spleens of mice treated with LVF have significantly less TNF-α, IL-6, IFN-γ, MCP-1, and MIP-1α 4 days after infection." (PMID 22428026, 2012). "Therefore, MyD88-dependent signal(s) appear responsible, in part, for IFN-γ, IL-6, and CXCL1 expression during late infection, although the mechanism(s) involved for targeting these factors remain to be identified." (PMID 22879997, 2012). "We found the production of Cxcl10 and Il-6 was strongly impaired in cells lacking Prkdc−/− or Xrcc5−/− during MVA infection whereas the response of these cells to infection by Newcastle disease virus (NDV, an RNA virus) remained intact." (PMID 23251783, 2012). "If applied 24 h post-infection rather than two hours, the significant 405 nm effect on IL-6 was lost." (PMID 22894815, 2012). "Strikingly, IL-6, IL-1β, IL-1α, IL-10, MIP-1α, and KC (data not shown) were secreted at significantly higher levels in response to infection with C. caviae compared to C. muridarum, whereas G-CSF (data not shown), GM-CSF (data not shown), and TNF-α levels were similar between the strains." (PMID 22292031, 2012). "The reduced level for IL-6, IL-1β, TNF-α, and IFN-γ in lung may be a reason for the enhanced morbidity in VK627 and rTsE627K infections." (PMID 22719870, 2012). "As seen during the natural infection, Shigella infection of rabbit ileal loops led to a large increase in mRNA abundance for the pro-inflammatory cytokines IL-1β, TNF- α, IL-6, IL-4, IFN-γ and IL-8, highlighting the similar cytokine response elicited in the two systems." (PMID 22675469, 2012). "The induction of IL-6 was dependent on viable virus as infection with UV-inactivated virus did not induce IL-6." (PMID 22962966, 2012).
infection (continued). "Both EV71 and CVA16 caused significant increases in IL-6 and RANTES mRNA levels; on the other hand, IL-10, NF-κB p65 and IL-1α were not elevated in RD cells 8 h after infection." (PMID 22666293, 2012). "Interestingly, DENV is able to trigger the expression of some proinflammatory cytokines (IL-6, IL-8, TNFα, and MIP-1β), a phenomenon observed at early times after infection." (PMID 22590678, 2012). "Infection of mice with HP H5N1 or pandemic 1918 H1N1 influenza virus led to the rapid infiltration of macrophages and neutrophils into the lungs, resulting in the acute inflammation with the production of inflammatory cytokines such as IL-1α, IL-6 and INF-γ." (PMID 21592354, 2011). "In addition, infection with the H1N1 virus produced a decreased expression of the innate immune genes tested, including Mx, IL-1β and IL-6 than observed with the H5N9 virus." (PMID 21939525, 2011). "Infection induced a robust 2W-specific Th17 cell response, which was dependent on the route of infection, IL-6, and was independent of superantigens." (PMID 21966268, 2011). "When cells were treated with UV-inactivated TCRV almost no release of IL-6 or IL-10 was detected, in contrast to infection with infectious TCRV." (PMID 21572983, 2011). "In the brains infected with Pigeon04, mRNA expression levels of Mx1, OAS, IL6, IL1β and CCL5 were at least 17 fold higher than those of respective genes in the infected lungs on day 5 post infection when this virus almost similarly replicated in the lungs and brains." (PMID 21826229, 2011). "Any elevation of CRP and IL-6 was thus interpreted to reflect inflammation secondary to benign or malignant biliary disease, rather than infection." (PMID 21970875, 2011). "Infection with wild type UPEC CFT073 and 536 as well all five PAI deletion mutants failed to induce IL-6 or TNF-α secretion and even suppressed the production of IL-6 below basal levels." (PMID 22164293, 2011). "The finding that Nippo mice have higher intraperitoneal IL-6 levels underscores the beneficial effects of locally produced IL-6 and suggests that increasing peritoneal IL-6 early in the course of infection benefits the host independent of its cellular source." (PMID 22110673, 2011). "Furthermore, expression of several key host defense genes, including cytokines (TNFα and IL6) and bactericidal molecules, such as defensin-4 (NP4), NOS2, NOX1 and ICAM1, peaked only at 8 and/or 12 weeks post-infection." (PMID 22645653, 2011). "On the other hand, and similar to B6 animals, AKR/J mice had undetectable levels of IL-10 even 48 h post-infection and no statistically significant increase in concentrations of IL-6, TNF-α, MCP-1 or KC." (PMID 21533108, 2011). "In untreated rabbits, most of these genes were progressively induced by Mtb infection from 4 to 8 weeks, and many had reached a plateau (IFN-γ, IL13, IL6, MIF, CCL4, NFκB, APRIL, TLR2, RAB7 and LAMP2) or were even reduced (IL10, CXCR3, GMCSF and PI3K3) by 12 weeks post-infection." (PMID 21949656, 2011). "Regarding the infection of microglial cells with M. tuberculosis and M. bovis, these microorganisms stimulated the production of IL-1A, IL-1B, TNF-α, G-CSF and GM-CSF; besides M. bovis stimulated the production also of IL-6." (PMID 22151930, 2011). "Further, IL-6 and IL-10 production were shown to be dependent on productive infection, while TNF-α production was not." (PMID 21572983, 2011). "The 2W:I-Ab+ cells from IL-6-/- mice had proliferated in response to infection with GAS-2W streptococci but failed to produce IL-17A." (PMID 21966268, 2011). "Though IL-6 is notably induced as a response to the LD50 infectious challenge (i.e. ratio significantly higher than 1.0), similar levels (p>0.1) were observed in hamsters whatever the outcome of the LD50 infection." (PMID 20076757, 2010).
infection (continued). "The factors elevated included A-SAA, a protein primarily synthesized by cells in the liver, high-level production of which is known to be induced during the acute phase response to infection, trauma or stress by pro-inflammatory cytokines including TNF-alpha, IL-6 and IL-22." (PMID 20463814, 2010). "Infection with Tn:Rv0431 resulted in greater expression of transcripts for IL-12p40, IL-6, Delta4, CD40, GM-CSF, RANTES, TNFα and MCP-1, but not GITRL or iNOS, than WT Mtb, both with (not shown) or without IFNγ costimulation." (PMID 21170273, 2010). "Specifically, we compared the induction of several pro-inflammatory cytokines (TNFα, IL6, IFNγ and MCP1) for changes in expression during infection by analyzing lung homogenates by CBA or quantitative RT-PCR to measure levels of mRNAs in Urbani virus or rMA15 virus infected mice, respectively." (PMID 20386712, 2010). "Nlrp3−/− mice had a modest but statistically significantly increase in IL-6 and TNF-α cytokines at 2 weeks (p = 0.026 and p = 0.028, respectively) and 5 weeks post-infection (p = 0.004, p = 0.001, respectively), but all differences were diminished by 16 weeks post-infection." (PMID 20808838, 2010). "Compared to sera from unchallenged control mice, serum levels of IFNγ (mean 7–21-fold increase), IL-6 (20–40-fold increase), and IL-17 (mean 8–12—fold increase) levels were significantly raised in immunized, but not un-immunized mice on day 2 of infection." (PMID 20967278, 2010). "Interestingly, the production of IL-6 and other cytokines seems transient after HBV infection, and HBV replication tends to increase after 3–4 days post infection when IL-6 level has already returned to baseline." (PMID 21994686, 2010). "It is noteworthy that IL-10 levels were maintained close to the basal level among infected animals on the 7th and 21st days p.i., while pro-inflammatory cytokine levels (TNF-α, CCL2, IL-6 and IFN-γ) presented a great variation among different experimental groups during the acute phase of infection." (PMID 20967289, 2010). "Major genes related to fever induction, IL6 and IL1B, were still up-regulated (16-fold and 4-fold respectively) in infected udder quarters 24 h after infection although the inner body temperature was already declining and approached basal levels at this time point." (PMID 20184744, 2010). "Similarly, at 18 hours post-H9N2/1997 infection, CCL-5/RANTES mRNA expression was found to be induced by nearly 1000 folds; while CXCL-10/IP-10, IL-6, and IL-8 were found to be up-regulated by 16-116 folds." (PMID 21108843, 2010). "The absence of CPS results in increased induction of IL-1β, IL-6 and IL-8 in human gingival fibroblasts upon in vitro infection with viable P. gingivalis cells." (PMID 20064245, 2010). "Seen especially in infants born before the completion of 34 weeks of gestation, amniotic fluid (AF) infection is often coupled with a proinflammatory response noted by the presence of cytokines such as tumor necrosis factor-alpha (TNF-α) and interleukin-6 (IL-6)." (PMID 20706662, 2010). "Thus, local and systemic levels of IL-6, IL1β, TNF-α, MIP-1α, and MIP-2 were compared between IL-4−/− and control mice at 2, 5, and 10 days after infection." (PMID 19606256, 2009). "At day 2 after infection significantly higher levels were evident only with regard to TNF-α production, but at the other time points assessed differences became statistically significant also for IL-6 and IL-1β production." (PMID 19606256, 2009). "In experimental aerogenous infection studies in pigs with the Gram-negative pulmonary pathogen Actinobacillus pleuropneumoniae, blood IL-6 was detected within the first 10–14 h PI." (PMID 19327150, 2009). "Interestingly, we observed a significantly reduced level of IL-6 and IFN-γ following infection of MyD88KO mice compared to WT NOD indicating that these cytokines are produced following ligation of TLRs other than TLR3." (PMID 19122812, 2009).
infection (continued). "In response to WT infection, however, there was a strong induction of IL-6 by day 2 post-infection, which preceded the induction of IL-17 and TNF-α, consistent with the established role of IL-6 in Th17 induction." (PMID 19759900, 2009). "After vaccination, infection induced a large increase in expression of IFN-γ especially on days 1 and 8 p.i., whereas vaccination dampened the infection-induced increases in mRNA levels for the proinflammatory cytokines IL1-β, TNF, and IL-6 – in particular around peak parasitaemia." (PMID 19341445, 2009). "Remarkably, while treatment with NTHi lysate acutely induces 8-fold more IL-6 and almost 40-fold more TNF than infection alone, the treated mice actually have lower levels of inflammatory cytokines in their lungs by day 3 after the infection." (PMID 19137067, 2009). "In response to CB3 infection, wt mice, but not IL-6KO mice, upregulated IL-6 with a peak in production at day 3 post infection indicating that IL-6 is involved in the early immune response following coxsackievirus infection." (PMID 19587788, 2009). "In this study, we found persistently high serum concentrations of IL-6 and IL-10 in patients with severe AP and in patients who developed infection, but not in patients with mild AP or uninfected patients." (PMID 19442309, 2009). "Following infection, mice lacking IL-6 developed increased chronic autoimmune disease pathology compared to wild type controls without a corresponding change in the level of viral replication in the heart." (PMID 19587788, 2009). "IL-6 together with IL-1 and tumor necrosis factor-α (TNF-α) are some of the major proinflammatory cytokines produced in monocytes and other cells as an immediate response to infection and other stimuli." (PMID 19327150, 2009). "In addition, the induction of the cytokines IL6, IL10, and the chemokine CCL2 occurred during acute infection." (PMID 20019816, 2009). "Upon infection by wild-type L. monocytogenes, IL-6 and TNF secretion was induced to a greater extent in xiap+/y macrophages than in xiap−/y macrophages, while infection with the LLO− mutant induced little IL-6 and TNF secretion by either genotype." (PMID 18769721, 2008). "Slightly more induction (1.02-fold) of IL-6 mRNA in cells without expressing the Flag-tagged eIF-3f was observed at 16 hour post-infection (lanes 3 and 7)." (PMID 18231581, 2008). "We find that in the absence of ISG15, infection with VVΔE3L produces an increase of IL-6 that correlates with short-term morbidity and complications that include pulmonary function abnormalities." (PMID 18604270, 2008). "From this data, we conclude that IFN-γ and IL-6 are not necessarily required for the control of ΔyopH infection at least in the early phase of infection." (PMID 18803824, 2008). "A similar trend was also detected with TNF-α, IL-6 and IFN-γ, 21 days after infection." (PMID 18798983, 2008). "Since the inflammatory response might explain the rapid signs of illness in VVΔE3L infected ISG15 KO mice, we measured serum cytokine levels (IL-6, TNF-α, IL-10, MCP-1, IFN-γ, and IL-12 p 70) at early times post infection." (PMID 18604270, 2008). "IL-6 mRNA showed a trend toward increased expression during infection, although the changes were not statistically significant." (PMID 18575603, 2008). "LPS stimulated splenocytes released comparable amounts of cytokine from the two groups of animals prior to infection but four days following Salmonella translocation, LPS stimulated TNF-α, IL-6 and MCP-1 release was significantly less in the B. infantis-fed animals." (PMID 18670628, 2008). "Virus-specific proliferation assays using 3H-thymidine incorporation were performed on WT and IL6−/− splenic CD4+ T cells, isolated either 2 weeks post infection (primary CD4+ T cell response), or at 8 weeks following a secondary infection (memory CD4+ T cell response)." (PMID 18389078, 2008).
infection (continued). "IL-6 levels returned to baseline levels following the establishment of the memory phase of the infection (data not shown)." (PMID 18389078, 2008). "Both the presence of IL-6 and TNF-α after inoculation in the two animals that remained clinically healthy could indicate a subclinical infection with B. hyodysenteriae." (PMID 18700003, 2008). "In accordance, the depletion of IFN-αβ-producing mDCs in mice prior to infection lowered, but did not entirely prevent the IL-6 response." (PMID 19008951, 2008). "IL-6 and CRP increased significantly more in patients with infections." (PMID 17505683, 2007). "Among them, IFN-α (1000 pg/ml at 16 h), IL1RA (750 pg/m), IL4 (13 pg/m) and the proinflammatory cytokines IL-6 (1250 pg/m) and TNF-α (1700 pg/m) were induced much more rapidly after MV-EDIII-ectoM infection and at levels 8–10 times higher than after MV-EDIII infection." (PMID 18160988, 2007). "The various activities of IL-6 and TNF-alpha suggest that thesefactors could play a major role in mediation of the inflammatoryand immune responses initiated by infection or injury." (PMID 17497030, 2007). "Infection with RV-16 (MOI of 4) significantly increased IL-6 secretion in both non-asthmatic (p < 0.001, n = 11) and asthmatic (p < 0.01, n = 8) -derived HASM cells in comparison to non-infected control cells 24 hours post infection." (PMID 16670028, 2006). "Infection with pneumococci or inhibition of JNK with SP600125 did not influence intracellular levels of IL-8 or IL-6 within the timeframe studied (data not shown)." (PMID 16834785, 2006). "As was observed in HASM cells grown to confluence, IL-6 secretion was induced 24 hours post RV-16 infection of both sub-confluent asthmatic, and sub-confluent non-asthmatic-derived HASM cells." (PMID 16670028, 2006). "Infection with RV-16 (MOI 4) and concurrent stimulation with 5% FBS significantly induced the release of IL-6 in comparison to 5% FBS alone in HASM cells derived from only non-asthmatic donors, whilst a non-significant trend towards increased production occurred in the asthmatic-derived cells." (PMID 16670028, 2006). "However, BALB/c splenocytes produced higher proinflammatory cytokines such as IL-1β, TNF-α, IL-6, IL-18 than C57BL/6 splenocytes after infection with B. pseudomallei." (PMID 16919160, 2006). "Interestingly, we observed that in vitro infection with H37Rv induced the whole blood cultures from HIV patients to synthesize increased levels of cytokines such as IL-1, TNF-α, IL-6 and IL-10." (PMID 16504020, 2006). "Notably, IL‐6 levels are reported to be significantly higher in secondary infections, particularly those involving DENV2, but not DENV1." (PMID 41488232, 2026). "The role of inflammatory cytokines (such as IL-6, IL-1 β, TNF - α) in inhibiting or regulating endogenous DKK1 expression has not been evaluated, and these factors may have an impact on local inflammation progression and fibrosis after AE infection." (PMID 40496021, 2025). "Although both IL-6 and CD11d were individually found to be significantly upregulated in the cardiac tissue of infected mice at 28 days post-infection compared to non-infected controls, Pearson correlation analysis showed no significant linear relationship between their expression levels." (PMID 41472298, 2025). "We found that both parent H1N1 and H1N1-E158A viruses induced cardiac IFNβ, TNF, IL-6, IL-18, and IL-1β above levels seen in mock control animals and that the H1N1-E158A virus induced higher levels of each inflammatory cytokine than the parent virus at day 5 post infection." (PMID 40909698, 2025). "However, indicating a broader inflammatory response in the whole brain, transcripts encoding pro-inflammatory cytokines, such as interleukin-1α (IL-1α), interleukin-6 (IL-6), interleukin-8 (IL8/CXCL1), and especially MCP1/CCL2, exhibited significant upregulation at 2- or 4-days post-infection." (PMID 40365287, 2025).